SRC (SRC proto-oncogene, non-receptor tyrosine kinase)
Diseases named in the same sentence as SRC in open-access papers (continued):
Sharing a sentence is not in itself a finding about the gene and the disease.
lung cancer (101 papers, 2010 to 2025). A malignant neoplasm involving the lung. "SRC mutation is involved in the malignant progression of many types of cancers, including lung cancer." (PMID 32419823, 2020). "Consistent with our findings, mutation and subsequent loss of the tumour suppressor function of NF1 has been reported in lung cancer cells which have acquired resistance to the SRC inhibitor dasatinib, and this was associated with active RAS-MAPK signalling." (PMID 29435137, 2018). "We next analyzed the biological consequences of the decreased SRC expression caused by miR-203 in lung cancer cells." (PMID 25140799, 2014). "One such target is SRC (also known as c-Src), a proto-oncogene encoding a tyrosine kinase that is frequently overexpressed and activated in many cancer types, including lung cancer." (PMID 25140799, 2014). "CTTN and SRC have been implicated in cell proliferation, motility, and invasion in various types of cancer, such as esophageal cancer, colorectal cancer, laryngeal carcinoma, and lung cancer." (PMID 31815134, 2019). "In this study, we further showed that ectopic expression of miR-203 could inhibit the translation of SRC in lung cancer cells, which, in turn, was associated with a reduction in the levels of Ras-GTP and phosphorylated-ERK1/2." (PMID 25140799, 2014). "Molecular alterations of YES1, a member of the SRC, can be found in a significant subset of patients with lung cancer." (PMID 38791306, 2024). "SRC promotes lung cancer cell invasion and metastasis through the activation of each TLR4-NF-κB pathway." (PMID 37763758, 2023). "SRC are frequently expressed and activated in lung cancer which involved in the proliferation, survival, angiogenesis, invasion, and migration of various types of cancer cells." (PMID 37770919, 2023). "A previous study showed that lung cancer cells that have undergone EMT can activate the FAK/SRC axis by altering the collagen composition of their surrounding microenvironment, leading to invasion and metastasis." (PMID 36684109, 2023). "EGFR-TKI-resistant lung cancer cells demonstrated that activation of off-target signaling molecules such as SRC, FAK, and YES, conferred resistance to various EGFR-TKIs17,24,25." (PMID 35643725, 2022). "In lung cancer cell lines insulin-like growth factor receptor (IGF-1R) inhibitor linsitinib treatment shortly decreased SRC activity but in a few hours SRC activity returned to an even higher level." (PMID 35392170, 2022). "It was observed that the mRNA expression of EGFR, MAPK1, Akt1, and SRC were upregulated in the lung cancer tissues whereas the expression of IGF1 and PI3KR1 was reduced as compared to the normal lung tissues." (PMID 36313358, 2022). "Together, AXL-induced growth signaling was associated with SRC and AKT activation in osimertinib-resistant lung cancer." (PMID 35643725, 2022). "According to previous studies, miR-203 inhibits the proliferation and migration of lung cancer cells and promotes apoptosis of lung cancer cells by targeting SRC expression." (PMID 36699068, 2022). "MiR-203 has been characterized to act as a tumor suppressor microRNA in laryngeal carcinoma by targeting survivin and in lung cancer by targeting v-src avian sarcoma viral oncogene (SRC) and protein kinase C alpha (PKCα/PRKCA)." (PMID 32806571, 2020). "In fact, SRC family kinases (SFKs) were overexpressed/overactivated in various malignancies, which was associated with poor disease progression and poor prognosis in patients with various cancers; for example, SRC was overexpressed in lung cancers." (PMID 31920968, 2019). "As SRC expression in lung cancer has previously been examined we focused on the expression of FYN and LYN using two different tissue micro arrays comprising 146 (TMA1) and 138 (TMA2) surgically resected NSCLC cases." (PMID 29937990, 2018).
lung cancer (continued). "Since both FAK and SRC were found to be activated in lung cancer cells chronically exposed to cigarette smoke, we assessed the potential role of FAK and SRC in regulating invasive potential in H358-S and a panel of NSCLC cells established from smokers." (PMID 29556515, 2018). "On the other hand, phosphorylation of EPHA2 promotes SRC activation and is involved in the acquisition of resistance of lung cancer cells to EGFR-TKIs." (PMID 29050315, 2017). "EGFR-independent SRC is also activated in other EGFR-TKI-resistant lung cancer cells, and dasatinib together with EGFR-TKIs overcomes drug resistance." (PMID 29050315, 2017). "In summary, this study provides the first clues regarding the role of miR-203 as a tumor suppressor in lung cancer cells through the inhibition of SRC translation." (PMID 25140799, 2014). "For example, the increased expression of SRC has been reported in 60–80% of adenocarcinomas and 50% of squamous cell carcinomas from lung cancer patients." (PMID 25140799, 2014). "MAP3K3 and MAP3K14 are in the MAPK/ERK pathway which is a target of many novel therapeutic agents, and SRC is a well known oncogene and a candidate target in lung cancer." (PMID 25170874, 2014). "miRNAs are, therefore, likely to play a biologically relevant role in regulating SRC expression in lung cancer." (PMID 25140799, 2014). "Despite these recent advances in our understanding of the important roles of SRC in tumorigenesis, the precise molecular mechanism through which SRC contributes to lung cancer progression remains to be fully elucidated." (PMID 25140799, 2014). "Taken together, this study delineates a novel regulatory network employing miR-203, SRC, and downstream signaling factors to fine-tune cell proliferation, migration, and apoptosis in lung cancer cells." (PMID 25140799, 2014). "Taken together, our results identified a miRNA as a link between the SRC regulatory pathway and the pathogenesis of lung cancer." (PMID 25140799, 2014). "In this study, we found that SRC protein levels were consistently upregulated in lung cancer tissues, but that SRC mRNA levels varied randomly, suggesting that a post-transcriptional mechanism was involved in SRC regulation." (PMID 25140799, 2014). "This disparity between protein and mRNA in SRC expression in lung cancers strongly suggests that a post-transcriptional mechanism is involved in SRC regulation." (PMID 25140799, 2014). "In AKT1 (r = −0.15, p < 0.05), BRAF (r = −0.25, p < 0.05), GAPDH (r = −0.3, p < 0.05), KRAS (r = −0.24, p < 0.05), MYC (r = −0.25, p < 0.05), and SRC (r = −0.24, p < 0.05), stromal score was negatively correlated with lung cancer and the highest correlation coefficient was in GAPDH." (PMID 39734333, 2024). "Notably, our study identified a negative correlation between the expression of key hub genes (AKT, BRAF, GAPDH, KRAS, MYC, and SRC) and immune and stromal cell content in the lung cancer TME." (PMID 39734333, 2024). "In osimertinib-resistant lung cancer cell lines harboring T790M mutation that we established, expression of multiple EGFR family proteins and MET was markedly reduced, whereas expression of AXL, CDCP1 and SRC was augmented along with activation of AKT." (PMID 35643725, 2022). "Activated SRC (p-SRC) is elevated in human ovarian, colorectal, breast, and lung cancers." (PMID 36362028, 2022). "Overexpression of SRPX2 boosts tumor progress by FAK/SRC/ERK pathway in lung cancer." (PMID 36385962, 2022). "In particular, SRC was overexpressed in most lung cancer samples in addition to either LYN or FYN." (PMID 29937990, 2018). "This together with the increased SFK activity seen in these cell lines suggested that SRC TKIs may be efficient therapeutic agents against lung cancer." (PMID 29937990, 2018). "In lung cancer cells, miR-203 was found to promote apoptosis through targeting SRC." (PMID 27935861, 2017). "Compensatory activation of SRC occurs in lung cancer cells with acquired resistance to EGFR-TKIs." (PMID 29050315, 2017).
lung cancer (continued). "Further, the FAK-SRC signaling pathway regulates the invasion of lung cancer and Ewing sarcoma cells, indicating that SRC may be a key therapeutic target for cancer treatment." (PMID 28640862, 2017). "We found previously that integrinβ1-driven SRC activation is involved in enhanced cell migration and invasiveness as well as the acquisition erlotinib-resistance in human lung cancer cells harboring activated mutant EGFR, and integrinβ1 knockdown or inactivation overcomes drug resistance." (PMID 29050315, 2017). "MiR‐203 suppresses cancer cell proliferation through the inhibition of SRC in lung cancer." (PMID 27489139, 2016). "However, the clinical application was limited by toxicity, and a more selective DDR2 inhibitor compounded with an SRC inhibitor was developed and demonstrated enhanced suppression of DDR2-mutated lung cancer cell lines." (PMID 27793038, 2016). "Its ten hub genes were extracted and confirmed in the literature; seven of them (UBC, SRC, SP1, MYC, STAT3, RB1, and MAPK1) were verified to be associated with lung cancer, while the remaining three genes, JUN, NR3C1, and GRB2, were potentially new candidate lung adenocarcinoma-related genes." (PMID 26402252, 2015). "Interestingly, it is noted that restoration of SRC expression can successfully attenuate the anti-proliferative, anti-migration, and pro-apoptotic effects of miR-203 on lung cancer cells, although miR-203 has many other targets." (PMID 25140799, 2014). "We found that SRC protein levels were dramatically higher in the lung cancer tissues." (PMID 25140799, 2014). "Consistent with this, we lastly showed that miR-203 could suppress SRC expression and, in turn, inhibit proliferation and migration and promote apoptosis of lung cancer cells." (PMID 25140799, 2014). "Additionally, high levels of SRC activity have been reported in lung cancer, particularly adenocarcinomas, and the degree of kinase activity correlates with tumor size." (PMID 25140799, 2014). "In addition,there is low miR-203 and high SRC expression in the majority of lung cancer tissues, and enforced expression of miR-203 clearly reduced the levels of SRC protein." (PMID 25004126, 2014). "Finally, we demonstrated that the repression of SRC by miR-203 suppressed the proliferation and migration and promoted the apoptosis of lung cancer cells." (PMID 25140799, 2014). "Interestingly, we identified discordance between the SRC protein and mRNA levels in human lung cancer tissue samples and cultured cells." (PMID 25140799, 2014). "Taken together, these results indicate that miR-203 might modulate cell apoptosis by downregulating SRC in lung cancer cells." (PMID 25140799, 2014). "Analyses of phosphoproteomic data from breast and lung cancer patient samples identified a subset of the SRC-dependent phosphorylation sites as being strongly correlated with SRC activation, which represent candidate markers of SRC activation downstream of receptor tyrosine kinases in human tumors." (PMID 21049007, 2010). "Therefore, the modulation of SRC by miR-203 might explain, at least in part, why the downregulation of miR-203 during lung carcinogenesis can accelerate lung cancer progression." (PMID 25140799, 2014). "We next investigated whether miR-203 was inversely correlated with SRC in lung cancer." (PMID 25140799, 2014). "In this study, we showed that silencing SRC expression using siRNA could inhibit cell proliferation and migration and promote apoptosis in lung cancer cells, while overexpressing SRC had opposite effects, validating its role as an essential oncogene during lung tumorigenesis." (PMID 25140799, 2014). "Analyses of phosphoproteomic data from breast and lung cancer patient samples identified a subset of the SRC-dependent phosphorylation sites as being strongly correlated with SRC activation, which represent candidate markers of SRC activation downstream of receptor tyrosine kinases in human tumours." (PMID 21967744, 2011).
lung cancer (continued). "Network pharmacological analysis identified PIK3CG, SRC, JAK3, AKT2, and PRKCA as key potential targets of peiminine in lung cancer treatment." (PMID 40331978, 2025). "exhibits significant anti-lung cancer potential by targeting key genes such as PIK3CG, SRC, and JAK3, as well as by modulating the PI3K-Akt signaling pathway and apoptosis-related genes." (PMID 40331978, 2025). "Collectively, these findings suggest that AKT1, EGFR, HSP90AA1, SRC, and STAT3 represent important therapeutic targets for anti-lung cancer intervention." (PMID 41465428, 2025). "Dasatinib, a multi-kinase inhibitor targeting BCR-ABL, SRC, and c-KIT, has been shown not only to inhibit the growth of lung cancer-derived CAFs but also to revert their oncogenic phenotype to that of non-tumorigenic fibroblasts." (PMID 41614761, 2025). "AKT1, EGFR, HSP90AA1, SRC, and STAT3 exhibited the highest degree values and were identified as core therapeutic targets for lung cancer." (PMID 41465428, 2025). "In the present study, SRC and YES1 exhibited elevated expression and activation in lung tissues from both lung cancer patients and mice exposed to radiation." (PMID 39776795, 2025). "Five core protein targets, AKT1, EGFR, HSP90AA1, SRC, and STAT3, were identified as potential mediators of steamed PJR’s anti-lung cancer effects." (PMID 41465428, 2025). "Five core targets, AKT1, EGFR, HSP90AA1, SRC, and STAT3, were identified as key mediators of its anti-lung cancer action, participating in critical signaling pathways including MAPK, PI3K-Akt, and Ras pathways." (PMID 41465428, 2025). "In our comprehensive study, we conducted molecular modelling analyses to identify potential drug candidates for targeting four key proteins involved in lung cancer: CDK2, SRC-2 domains of C-ABL, EGFR, and IGF-1R kinase." (PMID 38905286, 2024). "Targeting specific proteins such as SRC, STAT3, PIK3CA, MAPK1, EGFR, and JAK1 is crucial for impeding the growth of lung cancer." (PMID 38921583, 2024). "SRPX2 is invasive by upregulating the FAK/SRC/ERK pathway and can lead to pancreatic cancer drug resistance in PI3K/AKT in lung cancer." (PMID 34660598, 2021). "Expression of miR-150 is often deregulated in lung cancer, and it was shown to promote metastasis and proliferation of cancer cells by targeting FOXO4 and SRC kinase signalling inhibitor 149–51." (PMID 29679068, 2018). "For example, the combination of a SRC inhibitor and an EGFR inhibitor synergistically enhanced apoptosis in EGFR-dependent lung cancer cells." (PMID 27438149, 2016). "In a study of lung cancer cell lines using quantitative phosphoproteomics, approximately 40 different kinases were identified as dasatinib targets, including the SFKs LYN, SRC, YES, FYN, and LCK." (PMID 27756880, 2016). "Analysis of previously published RNA sequencing data from a series of osimertinib tolerant EGFR mutated lung cancer cell lines revealed higher expression levels of FYN and KDM4A in the drug persisters, but not SRC." (PMID 40243589, 2025). "This reduced DLC1 activity in human lung cancer was attributable to AKT and SRC kinase activities, both of which reduce the tumor suppressor activity of DLC1 via direct phosphorylation of specific tyrosines by SRC and specific serines by AKT28." (PMID 39528835, 2024). "Furthermore, miR-203 acts as a suppressor of the SRC/Ras/ERK pathway by inhibiting the expression of SRC oncogene, resulting in the suppression of proliferation and migration of lung cancer cells." (PMID 33803617, 2021). "Based on the importance of EGFR signaling in lung cancer, the known cooperation between EGFR and SRC proteins, and evidence of elevated SRC activity in human NSCLC, several studies have also evaluated the therapeutic effectiveness of SRC kinase inhibitors in lung cancer." (PMID 34944848, 2021).
lung cancer (continued). "Dasatinib (BMS-354825), a SRC/ABL inhibitor, effectively blocked SFK activation at nanomolar concentrations which correlated with a significant decrease in cell numbers of multiple lung cancer cell lines." (PMID 29937990, 2018). "After measuring the expression levels of miR-203 and SRC in human lung cancer tissue and paired noncancerous tissue samples, we detected an inverse correlation between miR-203 and SRC protein levels." (PMID 25140799, 2014). "As observed, an inverse correlation between the miR-203 levels and SRC protein levels, but not mRNA levels, was observed in human lung cancer tissues." (PMID 25140799, 2014). "We first investigated SRC expression by means of both immunohistochemical analysis and immunoblot analysis in human lung cancer tissues and corresponding noncancerous tissues." (PMID 25140799, 2014). "Additionally, the identified targets (PIK3CG, SRC, JAK3, AKT2, and PRKCA) may function as possible biomarkers for predicting lung cancer prognosis and guiding personalized therapy." (PMID 40331978, 2025). "In addition, the interaction of CD318 and SRC/FAK may promote anchorage-independent cell growth and metastasis in cancers, particularly in pancreatic cancer and lung cancer." (PMID 40725832, 2025). "Thus, ALK inhibition by ceritinib may lead to upregulation of SRC signaling, and AZD0530 could serve as a potential drug in the clinic to treat ALK‐resistant lung cancer patients." (PMID 28396832, 2017). "Finally, we showed that miR-203 inhibited SRC expression and consequently triggered the suppression of the downstream signaling pathways of SRC, such as the SRC/Ras/ERK pathway, which eventually suppressed the proliferation and migration and promoted the apoptosis of lung cancer cells." (PMID 25140799, 2014). "As expected, KAN0441571C induced dephosphorylation of ROR1 in a dose-dependent manner, as well as EGFR, SRC, PI3K110δ/AKT/mTOR (non-canonical Wnt pathway), and CREB in the NCI-H23 lung cancer cell line." (PMID 37111634, 2023). "Murine lung cancer cells lacking the Mir181ab1 cluster were more sensitive to the multiple–tyrosine kinase (BCR-ABL, SRC, c-KIT) inhibitor dasatinib than those cells in which Mir181ab1 was reconstituted." (PMID 31874105, 2020).